RN7SL163P (RNA, 7SL, cytoplasmic 163, pseudogene)
Gene: Miscellaneous RNA gene on chromosome 21 (17,506,453 to 17,506,728, forward strand). Ensembl gene ENSG00000266195.
Homologues: Orthologues: macaque Metazoa_SRP (75% identical). Paralogues in human: Metazoa_SRP (86% identical), RN7SL811P (86% identical), RN7SL134P (86% identical), Metazoa_SRP (84% identical), RN7SL96P (84% identical), RN7SL774P (84% identical), RN7SL784P (84% identical), RN7SL510P (83% identical), RN7SL596P (83% identical), Metazoa_SRP (83% identical), RN7SL474P (83% identical), Metazoa_SRP (82% identical), and 717 more.